ALK (ALK receptor tyrosine kinase)
Diseases named in the same sentence as ALK in open-access papers (continued):
Sharing a sentence is not in itself a finding about the gene and the disease.
cancer (continued). "Several ALK–TKIs have already been approved for use in the clinical treatment of specific cancers in some countries." (PMID 30400214, 2018). "The nucleophosmin (NPM)-ALK fusion gene was the first alteration in the ALK gene to be discovered in human cancers." (PMID 29455675, 2018). "Epidermal growth factor receptor (EGFR), anaplastic lymphoma kinase (ALK), v-raf murine sarcoma viral oncogene homolog B1 (BRAF), and c-ros oncogene 1 (ROS1) mutations are now used to guide specific anti-cancer therapies to improve patient outcomes." (PMID 30065223, 2018). "The existence of numerous diverse ALK fusion proteins suggests that the establishment of ALK fusion proteins through translocation is an important molecular mechanism of oncogenesis in multiple cancer types." (PMID 30400214, 2018). "In keeping with the pathogenetic importance of ALK in these human cancers, targeted inhibition of ALK using various tyrosine kinase inhibitors have shown therapeutic efficacy against subsets of ALK-positive tumors." (PMID 29535836, 2018). "Rearrangements of the ALK gene are present in in several human cancers and occur in approximately 5% of advanced NSCLC." (PMID 29507704, 2018). "ALK fusion proteins are usually found to activate downstream signaling pathways that contribute to related cancer pathogenesis." (PMID 30400214, 2018). "We found these cells showed a loss of ALK signaling, overexpressed AXL with epithelial-mesenchymal transition (EMT), and had cancer stem cell-like (CSC) properties, suggesting drug-tolerant cancer cell subpopulations." (PMID 29930762, 2018). "Ceritinib is currently undergoing phase I assessment as a monotherapy in relapsed or refractory ALK-positive paediatric cancers including NB (NCT01742286)." (PMID 29642598, 2018). "Because oncogenic activation of ALK kinase activity is crucial to ALK fusion proteins and ALK gain-of-function point mutants, inhibition of ALK kinase activity is the key to targeting ALK in various cancers." (PMID 30400214, 2018). "Our results have further substantiated the importance of the Wnt/β-catenin/MYC/Sox2 axis in conferring the cancer stem-like phenotype in ALK+ALCL." (PMID 29609590, 2018). "ALK-rearrangements are also common in other cancer entities, such as, for instance, in non-small cell lung cancer." (PMID 30558116, 2018). "The main mechanism of action of ceritinib is to inhibit the phosphorylation of ALK itself and ALK-mediated downstream signal proteins, thereby inhibiting the proliferation of ALK-positive cancer cells." (PMID 29455664, 2018). "We have demonstrated that cancer cell plasticity exists in ALK+ALCL, a type of hematopoietic cancer." (PMID 29609590, 2018). "ALK has been validated as a therapeutic molecular target for the treatment of ALK-rearranged cancer." (PMID 30006516, 2018). "This rise was due to alterations at a low percentage in genes with proven predictive value in the context of approved anti-cancer drugs (e.g., EGFR, BRAF, ERBB2, BRCA1, BRCA2, RET, ALK) in all cancer types." (PMID 29544535, 2018). "Compensatory TK signalling is observed in EGFR-TKI therapy, and KRAS, anaplastic lymphoma kinase (ALK), c-MET and BRAF mutations are also associated with poor responses to anti-EGFR therapy in some cancers." (PMID 29527128, 2018). "Several Food and Drug Administration (FDA)-approved drugs exist to target ALK fusions in lung and other cancer types." (PMID 29617662, 2018). "The strong anti-cancer effects of (S)-crizotinib in inhibiting GC cell growth likely indicate that these cells harbor alterations of ALK, ROS1, and or MET, although their precise genomic profile remains to be determined." (PMID 29855474, 2018). "ALK inhibitors can delay the progression of ALK-driven cancers, but are of limited use owing to ALK inhibitor resistance." (PMID 29760954, 2018).
cancer (continued). "Other trials are evaluating the safety and efficacy of second- and third-generation ALK inhibitors alone or in combination with chemotherapy and molecularly targeted compounds in patients with NB and other ALK-driven cancers." (PMID 29642598, 2018). "The immunological targeting of ALK thus provides a potent therapeutic option to treat ALK-positive human cancers." (PMID 29642597, 2018). "These potential new therapeutic strategies have the promise to improve the treatment of an increasing portion of patients ALK-positive cancers." (PMID 29495603, 2018). "Our study results also have provided further support that the Wnt/β-catenin/MYC/Sox2 axis is the key regulator of cancer stemness in ALK+ALCL." (PMID 29609590, 2018). "Because an increasing number of ALK fusion proteins are being identified in different types of cancers, we summarize the novel ALK fusion proteins that were found recently (from 2016 to 2018)." (PMID 30400214, 2018). "Such ALK mutations have been shown to hyperactivate the RAS–MAPK signaling pathway in NBL, driving cancer formation." (PMID 29441070, 2018). "Subsequent studies of ALCL and other types of human cancer have revealed additional fusion partners of ALK and various types of ALK gene aberrations." (PMID 29143801, 2017). "In this review, the molecular mechanisms of cancer stem cells in mediating resistance to ALK inhibitors as well as the current understanding of the molecular challenges in targeting ALK in ALK-expressing human cancers will be discussed." (PMID 29143801, 2017). "Its expression correlated strongly with ALK in an analysis of 1037 cancer cell lines (correlation coefficient = 0.92)." (PMID 27974674, 2017). "We recorded overexpression of cancer related genes including ALK, CDKN2A, and EZH2 compared with normal skin." (PMID 28359267, 2017). "With the application of next generation sequencing in the diagnosis of cancer patients, NSCLC cases harboring ALK genetic rearrangement concurrent with other somatic mutations have been detected." (PMID 29189709, 2017). "ALK is a member of receptor tyrosine kinase family and ALK translocations have been detected in various cancers, including NSCLC." (PMID 29088875, 2017). "Tyrosine kinases, such as ALK, are a very attractive therapeutic target for cancer treatment, especially on the basis of promising results from preclinical and early clinical studies." (PMID 29143801, 2017). "Chromosomal rearrangements in the ALK gene lead to the deregulation of ALK kinase activity, which in turn alters the downstream signaling pathways in cancer biology." (PMID 28245558, 2017). "Regardless of the particular derangement, the postulated central role of ALK in driving cancer progression raises the exciting possibility of using targeted therapies to treat ALK-positive cancer types." (PMID 28895885, 2017). "In summary, our study investigated ALK fusion detection based on two different commercially NGS-based approaches in FFPE-derived cancer specimens." (PMID 28970558, 2017). "In this review, the role of cancer stem cells and how it impacts on the resistance to ALK inhibitors as well as the current understanding of the molecular challenges in targeting ALK in ALK-expressing human cancers will be discussed." (PMID 29143801, 2017). "A new enzyme-linked immunosorbent assay (ELISA) was first developed to detect circulating ALK autoantibodies in the serum of cancer patients." (PMID 29190913, 2017). "Numerous genomic alterations have been found in correlation with oncogenesis and cancer progress, such as EGFR mutations, ALK-fusions, and KRAS mutations." (PMID 29285248, 2017). "Cancer cell invasion was abrogated when treating the cells with the low molecular weight inhibitor crizotinib (Xalkori®, Pfizer), that targets the RTKs ALK, MET and ROS." (PMID 29296175, 2017). "The article will summarize the role of ALK in disease pathogenesis, as well as current efforts to develop ALK-targeted cancer therapies for these malignancies." (PMID 28895885, 2017).
cancer (continued). "There is a growing body of evidence to support the potential development of a cancer vaccine targeting ALK as a shared antigen." (PMID 29190913, 2017). "Currently, the biological and clinical significance of double-positive, NLRR1-rich/ALK-poor, and NLRR1-poor/ALK-rich cancer cells remain to be uncovered." (PMID 27604320, 2016). "The prevalence of gene fusions involving kinases such as ALK, together with the relatively high success of targeting kinases in cancer, suggest that research focusing on inhibiting deregulated fusion kinases will continue to pay dividends." (PMID 27105842, 2016). "ALK is a member of the insulin receptor kinase superfamily, a large grouping which includes other tyrosine kinases of relevance to cancer such as MET and RON." (PMID 26755435, 2016). "Our findings extend the currently emerging paradigm for the design of HSP90 inhibition-based strategies, either alone or in combination with selective ALK targeting, in the management of ALK-driven resistant cancers." (PMID 26616860, 2016). "Aberrant expression of ROS1, ALK or c-MET (RAM) is implicated in carcinogenesis and cancer drug resistance." (PMID 27136744, 2016). "These single amino acid missense substitutions are located in the ALK tyrosine kinase domain and induce the constitutive activation of ALK by auto-phosphorylation, generating an oncogene that drives cancer progression." (PMID 27732954, 2016). "Given the importance of mTOR pathway, not only in ALK-related cancer, targeted therapy aimed to block its dysregulated downstream signaling has been widely investigated." (PMID 27662658, 2016). "Anaplastic Lymphoma Kinase (ALK) is a receptor tyrosine kinase aberrantly expressed in several cancers." (PMID 27385213, 2016). "Next, we used FISH to determine the absolute copy number at loci harboring cancer-relevant genes: ALK, ROS1, MET, BRAF and RET." (PMID 27100738, 2016). "Results from this study have strongly suggested that CETSA assay is a useful tool to predict Crizotinib sensitivity in ALK+ cancers." (PMID 27641368, 2016). "Our results have led us to conclude that the Crizotinib—ALK binding measurable by CETSA is useful in predicting Crizotinib sensitivity in ALK+ cancer cells, and Crizotinib—ALK binding is in turn dictated by structure of ALK and some of its binding partners." (PMID 27641368, 2016). "The third candidate gene, XLOC_215980 (Novel 3), resides on chromosome 6 and contains ALK (Anaplastic Lymphoma Kinase) domain, a tyrosine kinase receptor which has profound implications in multiple cancer types in humans." (PMID 26815362, 2016). "Anaplastic lymphoma kinase (ALK) is an important therapeutic target in cancer, despite the function of the wild-type protein being poorly understood." (PMID 27009859, 2016). "The rapid FDA approval of the first-generation ALK inhibitor crizotinib for first-line treatment of ALK-positive NSCLC in 2011 was a milestone in the history of clinical development of small molecular inhibitors to treat cancer." (PMID 26786851, 2016). "Recently, aberrant expression of Sox2 has been found in a relatively large number of cancer types, including breast cancer, melanoma, and ALK + ALCL." (PMID 27821172, 2016). "The development of ALK-targeted therapies, such as crizotinib, has changed treatment of ALK-driven cancers, presently most visible in ALK-positive NSCLC." (PMID 27483357, 2016). "Rather, it is also important to identify critical signalling components in the ALK interaction network that control pathways involved in cancer development and particularly resistance." (PMID 27669408, 2016). "The present study assessed the capability of entrectinib, a novel ALK tyrosine kinase inhibitor, to interfere with cancer cell growth, and proliferation." (PMID 26735175, 2016). "Overall, these findings indicate that ESRP1 is a key regulator of the EMT phenotype induced by oncogenic ALK in normal and cancer lung epithelial cells." (PMID 27119231, 2016).
cancer (continued). "In this study, we aimed to study the biology of Crizotinib resistance, by correlating various forms of ALK in a panel of ALK+ cancer cell lines and the in vitro sensitivity to Crizotinib." (PMID 27641368, 2016). "Our studies have provided direct evidence that Crizotinib—ALK interaction is the key determinant and predictor of Crizotinib sensitivity in these cancer cells." (PMID 27641368, 2016). "This enables ALK to maintain kinase activity that sustains cancer development despite high inhibitor concentrations." (PMID 27669408, 2016). "The most commonly mutated domain is the Tyrosine kinase domain observed in 20 different proteins, including such well-known cancer driver genes as ALK, EGFR or BRAF." (PMID 27150584, 2016). "Preclinical and clinical studies have shown that cancer cells harboring EML4-ALK are highly sensitive to ALK inhibition." (PMID 25899913, 2015). "One GC patient was partially IHC-positive, showing ALK cytoplasmic immunoreactivity in a proportion of cancer cells." (PMID 26678488, 2015). "Although ALK rearrangement has also been episodically observed in a small set of other cancer types, little is known about ALK rearrangements in MTC." (PMID 26295973, 2015). "IHC result of this patient was partially positive, showing cytoplasmic immunoreactivity for ALK protein expression in cancer cells with neuroendocrine differentiation." (PMID 26678488, 2015). "Despite the difference in cancer types and fusion partners, ALK rearrangements often lead to the constitutive activation of ALK." (PMID 26678488, 2015). "Previously, reports have shown that ALK tyrosine kinase receptor is a strong biomarker and a good therapeutic target for a significant number of cancer patients." (PMID 26384210, 2015). "In this fusion protein, the complete intracellular portion of ALK is preserved, and hence cancer cells harboring this fusion are sensitive to ALK tyrosine kinase inhibition." (PMID 26517679, 2015). "CRC is one of the most common cancers worldwide, utilizing this process to define the ALK gene-altered subset will benefit a great number of patients with CRC." (PMID 26678488, 2015). "Further functional studies are required that investigate the molecular mechanisms of ALK CNG upon cancer pathogenesis and the relationship between ALK CNG and ALK protein expression level." (PMID 25803816, 2015). "Some patients with late-stage non-small cell lung cancer (NSCLC) have rearrangements in the anaplastic lymphoma kinase (ALK) gene, and conventional cancer therapies are ineffective for these patients." (PMID 25951941, 2015). "Data on demographics, smoking history, cancer stage, histology, and EGFR/ALK mutation status were collected and analyzed." (PMID 26582178, 2015). "This compound led to inhibition of proliferation or induction of apoptosis in c-Met- and ALK-addicted cancer cells." (PMID 26405162, 2015). "On the other hand, many gene fusions involving oncogenes, such as those encoding ALK, RAF or FGFR kinase families, have been detected across multiple different epithelial carcinomas." (PMID 26684754, 2015). "Although crizotinib was ineffectual against EML4-ALK harboring the gatekeeper mutation, two structurally different ALK inhibitors, NVP-TAE684 and AP26113, were highly active against the resistant cancer cells in vitro and in vivo." (PMID 24722523, 2014). "Up until now, Crizotinib has been considered as the first-generation ALK inhibitor and have inhibited the activity of ALK in various cancers with ALK alteration." (PMID 25193856, 2014). "Anaplastic lymphoma kinase (ALK) genomic alterations have emerged as a potent predictor of benefit from treatment with ALK inhibitors in several cancers." (PMID 25083769, 2014). "The paracentric inversion causes a relatively close separation of the break-apart 3′ and 5′ ALK probes, which is harder to spot than rearrangements involving in different chromosomes seen in other ALK positive cancers, such as ALCL or IMT." (PMID 24667320, 2014).
cancer (continued). "Recently, EGFR- tyrosine kinase inhibitors (TKIs) and ALK inhibitors have been used widely in clinical settings as standard cancer therapies, and PTK-targeted therapies have demonstrated clinical success in the treatment of NSCLC." (PMID 24894011, 2014). "The ALKF1174L mutation is sensitive to the ALK inhibitor crizotinib only at high doses and mediates acquired resistance to crizotinib in ALK-translocated cancers." (PMID 25228590, 2014). "Among the 10 top-ranked compounds for ALK, eight compounds targeted cancer genes, and two out of the eight targeted ALK." (PMID 24565165, 2014). "For this reason, targeting ALK signaling has emerged as an attractive therapy in many types of ALK alteration cancers." (PMID 25193856, 2014). "The Pediatric Cancer Genome Project (PCGP) conducted a study of 40 patients with metastatic neuroblastoma and found mutations in ATRX and ALK in 22% and 14% of the patients correspondingly." (PMID 25528190, 2014). "In other words, the aberrant activity of ALK tyrosine kinase induced by EML4-ALK translocation results in less-differentiated carcinomas, more dangerous and aggressive types of cancers." (PMID 25407901, 2014). "In spite of the marked antitumor activity of crizotinib, ALK-positive cancers invariably gain resistance to crizotinib." (PMID 24842630, 2014). "Second, our pipeline was able to recapitulate most known translocation events in cancer (ALK, BRAF, EGFR, FGFR1, 2 and 3, NTRK1, 2 and 3, PDGFRA, PRKCA, RAF1, RET, ROS1)." (PMID 25204415, 2014). "Preclinical work demonstrated that cancer cells harboring EML4–ALK were highly sensitive to ALK inhibition." (PMID 25501361, 2014). "With the IHC analysis in this study, almost all of the cancer cells in the two cores showed ALK expression, despite the fact that only a few ALK+ cells were revealed by FISH analysis." (PMID 24422905, 2014). "We have found that ALK TK mRNA level (normalized to house gene ABL) in the EML4-ALK-positive carcinomas is significantly higher (p < 0.0001 by Mann–Whitney test) than in the EML4-ALK-negative samples." (PMID 25407901, 2014). "These remarkable results provide new therapeutic options for these very poor carcinomas and potentially for all carcinomas presenting an ALK rearrangement." (PMID 24475247, 2014). "Activation of several signaling pathways has been reported in human ALK-related cancers including MEK/ERK pathway involved in cell proliferation." (PMID 23667670, 2013). "Chromosomal rearrangements involving anaplastic lymphoma receptor tyrosine kinase (ALK), a member of receptor tyrosine kinase family, have been detected in various cancers." (PMID 23484153, 2013). "There was intratumor heterogeneity of ALK rearrangement in primary carcinomas and at metastatic sites." (PMID 23341890, 2013). "A recent report of rearrangements in anaplastic lymphoma kinase (ALK) receptor kinase as a possible mechanism for the tumorigenesis in this carcinoma opens the possibility of use of direct and indirect ALK inhibitors in the management of these patients." (PMID 24222876, 2013). "The promising results of anaplastic lymphoma kinase (ALK) inhibitors have changed the significance of ALK fusions in several types of cancer." (PMID 22347464, 2012). "Our findings will further expand the potential value of archival FFPE tissues and provide further biological and clinical insights into ALK-positive cancers in the forthcoming era of ALK inhibitor therapy." (PMID 22347464, 2012). "Some younger men have an echinoderm microtubule-associated protein-like 4 (EML4) and anaplastic lymphoma kinase (ALK) translocation (EML4-ALK), which causes their cancer." (PMID 22899945, 2012). "In a complementary, unbiased screen, mass spectrometry analysis of cancer cell supernatants identified PTN as the major ligand for the ALK ECD that had been immobilized on SELDI mass spectrometry chips." (PMID 23267434, 2012).